MIR1292 (microRNA 1292)
Synonyms: hsa-mir-1292; MIRN1292; mir-1292
Gene: MicroRNA gene on chromosome 20 (2,652,777 to 2,652,842, forward strand). Ensembl gene ENSG00000284481.
Diseases named in the same sentence as MIR1292 in open-access papers:
MIR1292 is named in the same sentence as 1 disease in open-access papers, as found by Europe PMC text mining. Sharing a sentence is not in itself a finding about the gene and the disease.
MIR1292 shares sentences with these, for which no sentence is quoted: breast carcinoma (1 paper).